IFT20 (intraflagellar transport 20)
Diseases named in the same sentence as IFT20 in open-access papers (continued):
Sharing a sentence is not in itself a finding about the gene and the disease.
lung adenocarcinoma (2 papers, 2022). A carcinoma that arises from the lung and is characterized by the presence of malignant glandular epithelial cells. "Interestingly, a positive correlation of IFT20 expression with reduced risk of metastasis and prolonged survival in patients with lung adenocarcinoma associated with specific clinicopathological features has recently been reported." (PMID 36292997, 2022). "A study reported that primary cilia frequency was significantly elevated in lung adenocarcinoma when compared with normal tissues, which may be partially caused by increased IFT20 expression in cancer cells." (PMID 35869490, 2022). "The aim of this study was to investigate the associations of intraflagellar transport protein 20 (IFT20) and Golgi matrix protein 130 (GM130) expression with clinicopathological features and survival in patients with lung adenocarcinoma." (PMID 35869490, 2022). "It is suggested that IFT20 might be a promoter of tumorigenesis, whereas it functions as a negative regulator in the progression of invasion and metastasis of lung adenocarcinoma cells." (PMID 35869490, 2022). "In conclusion, we found the expressions of IFT20 and GM130 protein were negatively associated with clinicopathological features including tumor differentiated types, size, TNM stage and lymphatic metastasis of lung adenocarcinoma." (PMID 35869490, 2022). "Cox proportional hazard regression models were conducted to evaluate the influence of IFT20 and GM130 protein expressions on the survival of lung adenocarcinoma patients after surgery." (PMID 35869490, 2022). "The expressions of IFT20 and GM130 protein were both positively expressed in cancerous and matched adjacent lung tissues of patients with lung adenocarcinoma." (PMID 35869490, 2022). "IFT20 and GM130 proteins have some protective effects on the survival of lung adenocarcinoma patients with specific clinicopathological features such as large tumor size and distant metastasis." (PMID 35869490, 2022). "Thus, it is indicated that IFT20 and GM130 protein could play crucial roles in the development of lung adenocarcinoma." (PMID 35869490, 2022). "However, we found a significantly negative association of IFT20 staining intensity score with clinicopathological features like TNM stage and lymphatic metastasis of patients with lung adenocarcinoma." (PMID 35869490, 2022). "Thus, both IFT20 and GM130 proteins might play important roles in the invasion and metastasis of various malignant tumors, but their roles in the tumorigenesis and development of lung adenocarcinoma remains unclear so far." (PMID 35869490, 2022). "Secondly, although both IFT20 and GM130 proteins are localized in the Golgi apparatus and interact with each other, their interaction and mechanism on the development of lung adenocarcinoma could not be evaluated." (PMID 35869490, 2022).
osteoporosis (2 papers, 2022 to 2024). A condition of reduced bone mass, with decreased cortical thickness and a decrease in the number and size of the trabeculae of cancellous bone (but normal chemical composition), resulting in increased fracture incidence. "By analysis of publicly available databases from bone samples of osteoporosis patients, we found that the expression of intraflagellar transport 20 (IFT20) and WW domain containing transcription regulator 1 (WWTR1) were significantly downregulated in osteoblast lineage cells." (PMID 38562782, 2024). "Moreover, IFT20 and WWTR1 deficiency in osteoblasts exacerbated bone-fat imbalance in ovariectomy (OVX)- and high-fat-diet (HFD)-induced osteoporosis mouse models." (PMID 38562782, 2024). "Importantly, this recent study identifies IFT20 as a promising drug target for the treatment of bone diseases such as osteoporosis and opens exciting new perspectives on the implication of IFT20 in other metabolic diseases." (PMID 36292997, 2022).
Anxiety (1 paper, 2025). Intense feelings of nervousness, tension, or panic often arise in response to interpersonal stresses. "By contrast, downregulation of Ift20 or Kif3a did not affect performance in the open-field test (OFT) and the light/dark test (LDT), indicating that exploratory-like and anxiety-like behaviors are unaffected." (PMID 39984747, 2025).
asthma (1 paper, 2023). "IFT20 deficiency in CD4+ T cells reduced airway inflammation in OVA-induced and protease-induced asthma models." (PMID 37029318, 2023). "To further assess the in vivo relevance of our findings, we analyzed IFT20 expression in existing transcriptomic datasets from human patients with asthma, which is a chronic respiratory disease characterized by variable expiratory airflow limitation." (PMID 37029318, 2023). "We then assessed the effect of IFT20 on asthma induction by exposing conditional IFT20-KO mice and WT mice to papain according to a defined schedule that induces allergic inflammation." (PMID 37029318, 2023). "In addition, asthma patients with acute exacerbation exhibited increased IFT20 expression in nasal lavage cells compared to that in a postexacerbation state, which is a stable state in asthma patients (GEO accession number GSE30326)." (PMID 37029318, 2023). "Notably, we found that the expression of IFT20 was increased in CD4+ T cells from patients suffering from asthma relative to those from healthy subjects (Gene Expression Omnibus (GEO) accession number GSE75011)." (PMID 37029318, 2023). "Thus, our results suggest that the development of asthma drugs targeting IFT20 may represent a possible strategy for treating severe refractory asthma patients." (PMID 37029318, 2023). "Therefore, we proceeded to investigate the role of IFT20 in asthma pathogenesis." (PMID 37029318, 2023).
autosomal dominant polycystic kidney disease (1 paper, 2019). Autosomal dominant form of polycystic kidney disease. "Two well-known ciliary receptors interact with IFT20, polycystin-2 (associated with the human autosomal dominant polycystic kidney disease), and opsins; however, a weak association was observed between IFT20 and CTS in these two receptors." (PMID 32010685, 2019).
chondrosarcoma (1 paper, 2019). A malignant cartilaginous matrix-producing mesenchymal neoplasm arising from the bone and soft tissue. "A recent report has described that IFT20 also regulates the nucleation of Golgi-derived microtubules, thereby promoting ribbon formation and polarized secretion in human chondrosarcoma cells." (PMID 30728324, 2019).
colitis (1 paper, 2022). Inflammation of the colon. "Consistent with the key role of IFT20 in IS assembly, conditional Ift20-deficient mice show defective antigen-specific T-cell responses due to defective proinflammatory cytokine production in mouse models of T-cell-driven colitis and collagen-induced arthritis." (PMID 36292997, 2022).
Impaired glucose tolerance (1 paper, 2022). An abnormal resistance to glucose, i.e., a reduction in the ability to maintain glucose levels in the blood stream within normal limits following oral or intravenous administration of glucose. "Interestingly, a significant increase in blood glucose levels and impaired glucose tolerance have been observed in tamoxifen-inducible Ift20 conditional knockout mice where Ift20 was specifically deleted in mesenchymal stem cells (MSCs) at the postnatal stage." (PMID 36292997, 2022).
Infertility (1 paper, 2025). "We reported that disruption of Ift20, Ift25, and Ift27 in male germ cells resulted in infertility." (PMID 40348912, 2025). "Likewise, IFT81 male mice were infertile associated with reduced IFT-B components in testes, and others, including IFT20, IFT25, IFT27, IFT57, IFT74, and IFT88, but there was no change in the IFT-A complex protein IFT140." (PMID 40348912, 2025).
Lymphatic Metastasis (1 paper, 2022). Transfer of a neoplasm from its primary site to lymph nodes or to distant parts of the body by way of the lymphatic system. "The adjusted odd ratio (OR) and 95% confidence interval (CI) for rate of IFT20 positive cells in the highest quartile was 0.44 (0.20, 0.93) in comparison with that in the lowest quartile for patients with lymphatic metastasis." (PMID 35869490, 2022). "Each one-point increase in the D value of IFT20 protein staining intensity score was significantly associated with a 32% and 29% reduced risk for TNM stage in II ~ IV and lymphatic metastasis of patients, respectively (P < 0.05)." (PMID 35869490, 2022). "With adjustment for multiple potential confounders, each one-point increase in IFT20 protein staining intensity score was significantly associated with 32% and 29% reduced risk for TNM stage in II ~ IV and lymphatic metastasis of patients, respectively (P < 0.05)." (PMID 35869490, 2022).
oral squamous cell carcinoma (1 paper, 2025). "This study explores the relationship between the alteration of primary cilia and tumourigenesis by investigating primary cilia expression and the role of IFT20 in regulating matrix metalloproteinase 9 (MMP-9) expression in oral squamous cell carcinoma (OSCC) cell lines." (PMID 40017656, 2025).
Osteopenia (1 paper, 2022). Osteopenia is a term to define bone density that is not normal but also not as low as osteoporosis. "Importantly, IFT20 plays a critical role in controlling bone formation not only during embryogenesis, but also in adults, as witnessed by the osteopenia-like phenotypes reported in the skull in the absence of IFT20." (PMID 36292997, 2022).
ovarian carcinoma (1 paper, 2012). A malignant neoplasm originating from the surface ovarian epithelium. "Initially, we investigated the expression and localization of two IFT proteins, IFT20 and IFT88, essential for the assembly of primary cilia and found no obvious difference between normal human OSE cells and the two ovarian cancer cell lines." (PMID 23351307, 2012).
primary immunodeficiencies (1 paper, 2025). "The data suggest a potential implication of IFT20 and TFEB defects in diseases characterized by impaired CTL function, of which prominent ones are primary immunodeficiencies and cancer." (PMID 40389449, 2025).
Renal cyst (1 paper, 2022). A fluid filled sac in the kidney. "Mice with double mutations in Pkd1 and Kif3a or in Pkd2 and Ift20 exhibited an intermediate phenotype between the milder cilia-induced and more severe polycystin-induced cystic kidneys." (PMID 35253003, 2022). "Mice with mutations in ciliary assembly genes (Kif3a, Ift88, Ift140, Ift20) develop renal cysts." (PMID 35253003, 2022).
cancer (10 papers, 2012 to 2025). A tumor composed of atypical neoplastic, often pleomorphic cells that invade other tissues. "One central question is whether the lysosomal defect in IFT20-deficient T cells might impinge not only on the activation but also on the activity of cytotoxic T cells, which are responsible for the elimination of infected or cancer cells." (PMID 31803744, 2019). "Meanwhile, IFT20 promotes cancer cell migration and invasion via vesicular transport of signalling molecules and transmembrane protein, polarised localisation of Golgi complex, and regulation of microtubule dynamics." (PMID 40017656, 2025). "By maintaining only one metabolic pathway, cancer cells with a GLI1+/IFT20+ signature offer a metabolic vulnerability that we would be wise to exploit." (PMID 32194829, 2020). "Thus, even though the role of IFT20 in cancer needs to be explored in more depth, these findings suggest that IFT20 could play important roles also during tumorigenesis." (PMID 36292997, 2022). "Further, WB analysis of lysates from wt and cancer OSE cell cultures grown with or without serum demonstrated that IFT88 and IFT20 are expressed at similar levels in all three OSE cell lines." (PMID 23351307, 2012).
tumor (8 papers, 2010 to 2025). "The association between IFT20 expression, ciliary dynamics, and tumour heterogeneity also opens intriguing possibilities for ciliotherapy, a therapeutic strategy aimed at targeting primary cilia and their associated proteins." (PMID 40017656, 2025). "Thus, these additional findings further linked the ability of IFT20 to regulate Golgi ribbon formation with its role in mediating tumor invasiveness and invadopodia formation induced by Ror2 signaling." (PMID 28127051, 2017). "The IFT20 and GM130 protein expressions were only negatively associated with the death risk of patients with specific clinicopathological feature such as tumor size > 7 cm or distant metastasis." (PMID 35869490, 2022). "Initially examining SaOS2 cells as a model tumor, we find that Ror2 signaling promotes the expression of IFT20." (PMID 28127051, 2017). "We then find that IFT20 mediates the ability of Ror2 to promote the invasiveness of these tumor cells." (PMID 28127051, 2017). "We also confirmed that IFT20 mediates the effect of Ror2 signaling in these tumor cells, as the ectopic overexpression of IFT20 reverted the effect of siRNA against Ror2." (PMID 28127051, 2017). "These seemingly paradoxical effects of IFT20 could be explained by a dual role of primary cilia mediated Hh signaling activation and suppression in oncogenesis and tumor progression." (PMID 35869490, 2022). "Thus, as in the case for tumor invasion and invadopodia formation, as well as the regulation of Golgi structure, IFT20 also mediates the regulation of Golgi-derived MTs by Ror2 signaling." (PMID 28127051, 2017). "The link between the regulation of the Golgi by IFT20 and its role in mediating tumor invasiveness induced by Ror2 signaling is further strengthened by our additional finding that AKAP450 is also needed for the ability of Ror2 signaling to promote tumor invasion and invadopodia formation." (PMID 28127051, 2017). "We also examined whether IFT20 regulates the Golgi structure similarly in other tumor cells whose invasiveness might be promoted by the constitutive activation of Ror2 signaling." (PMID 28127051, 2017). "Thus, we next examined whether IFT20 is involved in this polarization during tumor cell invasion." (PMID 28127051, 2017). "Adding to this mechanistic understanding, we show that IFT20 promotes the GM130-AKAP450 interaction to nucleate Golgi-derived MTs, resulting in Golgi ribbon formation being promoted for tumor invasiveness." (PMID 28127051, 2017). "In contrast, we have found in non-ciliated tumor cells that IFT20 regulates the role of AKAP450 in nucleating MTs for Golgi ribbon formation." (PMID 28127051, 2017). "In these cells, IFT20 at the early endosome has been found to regulate endocytic recycling, while we have found that the Golgi pool of IFT20 in non-ciliated tumor cells regulates Golgi structure and transport." (PMID 28127051, 2017). "Here, we uncover a new non-ciliary role of IFT20, acting to regulate Golgi structure and transport, and also find that this role mediates the ability of constitutively activated Ror2 signaling to promote tumor invasiveness." (PMID 28127051, 2017). "Notably, multiple tumor types lose their cilium during transformation, but IFT20 is still expressed in these non-ciliated tumor cells." (PMID 28127051, 2017).
inflammation (1 paper, 2023). Aberrant reaction of the microcirculation characterized by movement of fluid and leukocytes from the blood into extravascular tissues. "Finally, mice with T-cell-specific IFT20 deficiency exhibited reduced allergen-induced airway inflammation." (PMID 37029318, 2023). "Notably, we detected substantial goblet cell hyperplasia and infiltration of various immune cells that are hallmarks of airway inflammation in papain-treated WT mice but not in papain-treated IFT20-KO mice." (PMID 37029318, 2023).
IFT20 also shares sentences with these, for which no sentence is quoted: achondroplasia (1 paper); Arthritis (1); frontometaphyseal dysplasia (1); hepatocellular carcinoma (1); hydrocephaly (1); liver cirrhosis (1); lung carcinoma (1); Meckel syndrome type 13 (1); Meckel syndrome, type 2 (1); metabolic disease (1); Osteoblastoma (1); osteofibrous dysplasia (1); polydactyly (1); spondylometaphyseal dysplasia (1); varicocele (1).